PIK3CA (phosphatidylinositol-4,5-bisphosphate 3-kinase catalytic subunit alpha)
Diseases named in the same sentence as PIK3CA in open-access papers (continued):
Sharing a sentence is not in itself a finding about the gene and the disease.
tumor (continued). "In addition to the SOLAR-1, another study (i.e., BYLieve) showed that PIK3CA testing can be carried out on tumor tissue specimens (primary tumor or metastasis) and/or in circulating tumor DNA (ctDNA)." (PMID 36428975, 2022). "The main clone would develop PIK3CA p.(Glu542Lys), populating the primary tumor." (PMID 35682999, 2022). "Compared to patients without PIK3CA mutation, more tumor shrinkage was observed in those with PIK3CA mutation after treatment with alpelisib." (PMID 38089455, 2022). "Meanwhile, PIK3CA E545K mutation was identified in tumor tissue and plasma of P05 and 12, and no other known driver mutation was identified in both cases." (PMID 35402276, 2022). "Thus, the addition of the AKT inhibitor capivasertib resulted in significantly longer PFS, and the benefit was more pronounced in patients with PIK3CA/AKT1/PTEN-altered tumours." (PMID 35954393, 2022). "No PIK3CA or CDKN2A variants were detected in the 9 paraffin-embedded tumor specimens in this study." (PMID 36289533, 2022). "Given that the PIK3CA mutation is frequent in BCs, PD-L1, c-Met, and MSI/dMMR might considerably affect BCs, thus, implying that these markers would be tumor behavior-related biomarkers for PIK3CA-mutated BC." (PMID 35621626, 2022). "A greater understanding of the LAR group has led to the ongoing evolution of therapeutic combinations, including those of AR inhibitors with PI3K inhibitors given the frequent co-amplification of PIK3CA in AR-positive tumours, which is estimated to be as high as 40%." (PMID 35877237, 2022). "One patient had a PIK3CA mutation in the primary tumor but not in the brain metastasis, and five patients harbored new mutations in their brain metastasis tumors only." (PMID 36507516, 2022). "Notably, tumor regression (TGI > 100%) was only observed in palbociclib plus alpelisib-treated groups in two PIK3CA-amplified models, SHHN001 and SHHN003 with a TGI = 107.45% and 103.66%, respectively." (PMID 35546399, 2022). "Since we had demonstrated that the combination of Alpelisib and Tazemetostat induced tumor regression of PIK3CA E545K mutant tumors, we next tested if the drug combination induced regression of tumors harboring the other two recurrent PIK3CA helical domain mutations (E542K and Q546P)." (PMID 35418124, 2022). "In addition, copy number amplification of PIK3CA and copy number loss of PTEN are very frequent in tumour samples with high SCS." (PMID 35326573, 2022). "Capivasertib and ipatasertib (both AKT inhibitors) have both demonstrated clinical activity in combination with paclitaxel in triple-negative-breast cancer (TNBC) in Phase II clinical studies, with more pronounced benefit in patients with PIK3CA/AKT1/PTEN mutant tumours." (PMID 36241868, 2022). "Moreover capivasertib has also demonstrated single-agent clinical activity in patients with BC harbouring AKT1 and PIK3CA mutant tumours and germ-line PTEN alterations." (PMID 36241868, 2022). "The tumor burden mutations (TMB) correlation analysis showed that high TMB had a worse prognosis than low-TMB, and gene mutations were found to be different in high and low TMB groups, such as PIK3CA (36% versus 32%), SYNE1 (4% versus 6%)." (PMID 36203428, 2022).
tumor (continued). "Furthermore, LAR tumours and cell line models display high dependencies on AR, FOXA1, ERBB2, and AKT protein and phospho-protein signalling, as well as frequent PIK3CA and ERBB2 mutations." (PMID 36077812, 2022). "Conversely, adjuvant chemotherapy and lack of PIK3CA mutations were associated with better OS and high tumor infiltration by CD8+ cells with longer RFS." (PMID 33673133, 2021). "In elderly HGSOC, mutations in the genes that are involved in the Ras and or PIK3CA signaling pathways were detected in nine samples (15%), including the genes KRAS and BRAF (each one in 1 tumor); PIK3CB and MTOR (each one in 2 tumors); and NF1 (in three different samples)." (PMID 34944094, 2021). "Moreover, mutant PIK3CA can affect tumor cellular proliferation and invasion, tumor metastasis, and patients' survival." (PMID 34367282, 2021). "All participants, regardless of tumour PIK3CA mutation status, had detectable PIK3CA mutations in their plasma ctDNA at varying quantities." (PMID 33799597, 2021). "Moreover, for subgroup analyses based on race, gender, age, KIRC subtypes, tumor grade, cancer stages, and nodal metastasis status, PIK3CA mRNA expression was also significantly lower in tumor tissues than in normal tissues." (PMID 34367282, 2021). "This leads us to propose a hypothesis that FSCN1 may have a pro-tumor function among patients with PIK3CA alterations." (PMID 34249689, 2021). "Therefore, it is possible that the increased tumor growth in Ace-1-Dkk-1YFP-LUC xenografts was related to the upregulated expression of PIK3CA." (PMID 34437475, 2021). "The LCM analysis showed that in some cases, all epithelial components had the same hotspot mutation as the original tumor part (cases c, f, and h), while in others, some epithelial components did not have PIK3CA mutation (cases b and g)." (PMID 34172890, 2021). "Specifically, we included mainly patients whose tumours harboured PIK3CA mutations, FGFR or DNA repair alterations (non-BRCA)." (PMID 34493820, 2021). "We investigated the frequency of PIK3CA c.3140A>G p.(His1047Arg) in population datasets not enriched for tumor associated phenotypes." (PMID 34075207, 2021). "Preclinical and clinical data in different tumor entities indicate that activating PIK3CA alterations may predict sensitivity to therapies targeting PI3K or AKT." (PMID 34202213, 2021). "Among the 14 cases of OCCC with PIK3CA mutation, only three cases (21.4%) had PIK3CA mutation with MAF ≥ 15% in the eutopic endometrial glandular epithelium in a single hotspot coincident with the tumor (cases b, g, and h)." (PMID 34172890, 2021).
tumor (continued). "Copy number aberration (CNA) profiling and variant analysis using next-generation sequencing (NGS) showed that these cells did not harbor the alterations exhibited by the primary tumor (PIK3CA G1049A mutation, MYC copy number gain)." (PMID 34249978, 2021). "This suggests that FSCN1 may play a key role in PIK3CA-altered tumor cells and that the survival of PIK3CA-altered tumor cells under radiotherapy treatment may be specifically accompanied by high expression of the FSCN1 gene." (PMID 34249689, 2021). "We next investigated whether mutation of PIK3CA is sufficient to confer AKT-mTOR signaling and tumor resistance to CDX-3379." (PMID 33888713, 2021). "Broader genetic profiling by NGS of baseline ctDNA samples revealed co-occurring alterations in PIK3CA in 9/28 (32%) patients with sufficient tumor DNA for analysis, a slightly greater rate than that (19–20%) reported by The Cancer Genome Atlas and METABRIC analyses." (PMID 33863913, 2021). "Mutation types found within the PIK3CA gene were missense in six tumors (H1047L in No. 5, H1047R in No. 7, 16, and 19, C420R in No. 9, E453K in No. 18) and in-frame deletion in one tumor (V105_R108del in No. 1)." (PMID 33854152, 2021). "Our exploratory analysis revealed that, despite having similar tumor mutation burden, MBCs harboring TERT genetic alterations were significantly enriched for PIK3CA clonal mutations preferentially affecting hotspots (5/6, 83% TERT altered vs 5/38, 13% TERT WT; p = 0.001, Fisher’s exact test)." (PMID 33863915, 2021). "The percentage of tumor cells with PIK3CA mutations was not defined in these cases, and it is not clear how widespread mutations in PIK3CA must be to influence therapeutic response in HCC." (PMID 34771685, 2021). "As mutations in PIK3CA and ER genes appeared during the course of therapy, CTC lines harboring these mutations responded to different agents such as PIK3CA inhibitors and ER inhibitors, in comparison with the primary tumor." (PMID 33578862, 2021). "This suggested that PIK3CA-altered tumor cells may specifically rely on FSCN1 to survive radiotherapy treatment." (PMID 34249689, 2021). "There is evidence suggesting that PIK3CA hotspot mutations do not always capture all PI3K-dependent tumor genotypes that potentially respond to PI3K inhibitors." (PMID 33801659, 2021). "Besides mutations in PIK3CA and PIK3CB genes, inactivating events also occur in tumor suppressors such as PTEN." (PMID 34298731, 2021). "We found one study dealing with cell-free DNA in 19 patients with IBC, but only one PIK3CA mutation was found in tumour samples without circulating corresponding mutations." (PMID 34911971, 2021). "The treated tumor showed several CNVs in driver genes, including amplifications in MCL1, TERT, CCND1, AKT1, MYC, EGFR, and FGFR3; deletions in CDK1B, CDKN2A and CDKN2B; a PIK3CA hotspot mutation; and a high TMB." (PMID 34680239, 2021). "In that regard, it has been shown that the loss of PIK3CA function led to multifocal sites of epithelial hyperplasia but with no development to tumor formation." (PMID 34680390, 2021).
tumor (continued). "One case had a recurrence without a PIK3CA mutation detected in her tumor DNA or circulating cfDNA collected before treatment; however, this case did not have cfDNA samples collected during follow-up for testing the PIK3CA mutation." (PMID 34203201, 2021). "This is concordant with work showing that while the mutated loci of PIK3CA exhibit varying downstream effects in proportion to their recurrence in tumor cohorts, these effects differ primarily in degree, not in kind." (PMID 33957863, 2021). "It is notable that in the BOLERO-2 study, the benefit from everolimus was not influenced by the presence of PIK3CA tumor mutations." (PMID 34885105, 2021). "The most impressive data we obtained in this study were the high frequency of eutopic endometrial glandular epithelium-specific PIK3CA mutations in OCCC cases without PIK3CA mutations in the tumor." (PMID 34172890, 2021). "In order to explore whether the key genes showed somatic mutations in EC, we detected mutations in tumor-related genes and found PTEN (71.46%), PIK3CA (50.6%) and ARID1A (40.77%) were most frequently mutated genes." (PMID 33495413, 2021). "High γδ T cell infiltration was associated with better survival in patients with PIK3CA wild-type tumors, without significant difference in the PIK3CA-mutated tumor subgroup." (PMID 33673133, 2021). "PIK3CA mutation detected in archival tumour tissue did not appear to predict tumour response to copanlisib and trastuzumab in this small, heavily pre-treated cohort." (PMID 33799597, 2021). "Conversely, in two cases with PIK3CA mutations with MAF ≥ 15% in a single hotspot in the eutopic endometrial stroma consistent with the tumor, the PIK3CA mutations in the epithelial component of the tumor were homogeneous (cases c and f)." (PMID 34172890, 2021). "According to the synthetic lethal theory of tumor cells, alterations in the PIK3CA oncogene may lead to potential defects in tumor cells so that they would be specifically dependent on the activation of certain pathways or on the expression of certain genes." (PMID 34249689, 2021). "Similar to the results in eutopic endometrium, PIK3CA mutations in the endometriotic epithelium coexisting with OCCC were not identical to those in the tumor." (PMID 34172890, 2021). "Conversely, molecular apocrine tumors, defined as AR- and FOXA1-expressing tumors that frequently harbor PIK3CA mutations, were more frequently associated with a “cold tumor” phenotype (i.e., low TIL density and absence of PD-L1 expression)." (PMID 33673133, 2021). "Consistently, FSCN1 knockdown promoted cell apoptosis in tumor cells with PIK3CA alterations." (PMID 34249689, 2021). "Furthermore, T cell exclusive phenotype is also observed in tumor with PI3K pathway activation or genomic gain in PIK3CA or PIK3CB." (PMID 33874915, 2021). "PIK3CA is involved in tumor progression and multidrug resistance, thus affecting overall survival." (PMID 34367282, 2021). "That is probably because tumor tissues could inhibit the level of PIK3CA or PIK3CA served as a tumor suppressor in KIRC." (PMID 34367282, 2021). "These genomic alterations (point mutations or amplification) in PIK3CA result in hyperactivation of the PI3K pathway, leading to cellular transformation and to enhanced tumor cell growth, survival, and motility, all of which contribute to tumor progression." (PMID 34067117, 2021).
tumor (continued). "Five mutations in PIK3CA, one in BRCA1 and one in IDH1 found in this study are FDA-recognized biomarkers (level 1) and one ERBB2 mutation is a standard care biomarker (level 2A), predictive of response to FDA-approved drugs in specific tumor types." (PMID 33500480, 2021). "PIK3CA is the most frequent tumor alteration in SCCAC, reported in up to 40% of patients." (PMID 34729104, 2021). "Besides these two important GC driver genes, APC and PTEN tumour suppressor driver genes, as well as KRAS and PIK3CA driver oncogenes, were also transversally mutated in both GC histotypes with frequencies below 15% across data sets." (PMID 33724653, 2021). "CDK4/6i+ET combinations were the most effective treatment in the first-/second-line settings irrespective of tumor metastatic distribution and PIK3CA mutational status, as well as in endocrine-sensitive tumors." (PMID 33810205, 2021). "The tumor tissues were subjected to whole exome sequencing (WES) and four mutations with potential clinical significance were identified: CDKN2A deletion, CDK6 amplification, PIK3CA amplification, and KRAS G12V mutation." (PMID 34327143, 2021). "Therefore, PIK3CA can affect tumor proliferation, invasion, apoptosis, and angiopoiesis in KIRC by regulating MAPK1 and EGFR." (PMID 34367282, 2021). "PIK3CA AF showed a marked increase in the donor’s lesions over the 10 d separating the collection of the TF at the time of the hematoma evacuation and the first tumor resection even if both had equivalent tumor purity." (PMID 34301805, 2021). "The FDA also recommends that patients who progressed on AI and have negative ctDNA PIK3CA-mutation tests should undergo tumor biopsy for PIK3CA-mutation assessment." (PMID 34771560, 2021). "In OCCC cases without PIK3CA mutation in the original sample of the tumor, neither the additional macrodissection sample nor the LCM sample had PIK3CA mutation (cases i–k)." (PMID 34172890, 2021). "In the randomized phase III BELLE-2 study, which examined the efficacy of the PI3K inhibitor buparlisib in patients with hormone receptor-positive, HER2 negative breast cancer, PIK3CA mutation in tumor tissue and ctDNA was investigated." (PMID 33249514, 2021). "Having established the phenotypic changes in the HMOsisEC10 KRAS and HMOsisEC10 PIK3CA mutant epithelial cell lines, we next examined whether these cells showed altered tumor growth in nude mice." (PMID 34202354, 2021). "While the combined E6, E7 and Pik3ca mutations resulted in spontaneous ASCC formation in the absence of DMBA, the presence of Pik3ca mutations alone were sufficient to lead to tumor formation with DMBA application." (PMID 34062753, 2021). "One patient did not have a tumor sample available, but the baseline plasma contained a PIK3CA mutation." (PMID 34298704, 2021).